LCAT (lecithin-cholesterol acyltransferase)
Description:
Central enzyme in the extracellular metabolism of plasma lipoproteins. Synthesized mainly in the liver and secreted into plasma where it converts cholesterol and phosphatidylcholines (lecithins) to cholesteryl esters and lysophosphatidylcholines on the surface of high and low density lipoproteins (HDLs and LDLs). The cholesterol ester is then transported back to the liver. Has a preference for plasma 16:0-18:2 or 18:O-18:2 phosphatidylcholines. Also produced in the brain by primary astrocytes, and esterifies free cholesterol on nascent APOE-containing lipoproteins secreted from glia and influences cerebral spinal fluid (CSF) APOE- and APOA1 levels. Together with APOE and the cholesterol transporter ABCA1, plays a key role in the maturation of glial-derived, nascent lipoproteins. Required for remodeling high-density lipoprotein particles into their spherical forms. Catalyzes the hydrolysis of 1-O-alkyl-2-acetyl-sn-glycero-3-phosphocholine (platelet-activating factor or PAF) to 1-O-alkyl-sn-glycero-3-phosphocholine (lyso-PAF). Also catalyzes the transfer of the acetate group from PAF to 1-hexadecanoyl-sn-glycero-3-phosphocholine forming lyso-PAF. Catalyzes the esterification of (24S)-hydroxycholesterol (24(S)OH-C), also known as cerebrosterol to produce 24(S)OH-C monoesters.
Tractability: Small molecule: a structure with a bound ligand is known; a high-quality ligand is known. Antibody: UniProt places it where antibodies can reach, with high confidence; its Gene Ontology location is reachable by antibodies, with high confidence; UniProt predicts a signal peptide or a membrane-spanning region. PROTAC: a small molecule that binds it is known.
Target class: Enzyme; Transferase
Gene: Protein-coding gene on chromosome 16 (67,939,750 to 67,944,131, reverse strand). Ensembl gene ENSG00000213398.
Subcellular location: Secreted
Subcellular location (Human Protein Atlas): Nucleoplasm; Predicted to be secreted
Pathways (Reactome):
Transport of small molecules: HDL remodeling
Gene Ontology:
Molecular function: 1-alkyl-2-acetylglycerophosphocholine esterase activity; apolipoprotein A-I binding; phosphatidylcholine-sterol O-acyltransferase activity; platelet-activating factor acetyltransferase activity; protein binding; sterol ester esterase activity; phospholipase A2 activity
Biological process: cholesterol homeostasis; cholesterol metabolic process; cholesterol transport; high-density lipoprotein particle remodeling; phosphatidylcholine biosynthetic process; phosphatidylcholine metabolic process; phospholipid metabolic process; reverse cholesterol transport; very-low-density lipoprotein particle remodeling; lipid metabolic process; lipoprotein metabolic process; regulation of high-density lipoprotein particle assembly; response to copper ion; response to glucocorticoid
Cellular component: extracellular exosome; extracellular region; high-density lipoprotein particle
Genetic constraint (gnomAD): Loss-of-function variants: 15 observed, 40.63 expected, observed/expected ratio (o/e) 0.37, 90% interval 0.25 to 0.57. The upper end of that interval is the gene's LOEUF score, 0.57, which puts it in group 2 of 6, group 1 being the genes least tolerant of losing a copy. Missense variants: 449 observed, 608.91 expected, observed/expected ratio (o/e) 0.74, 90% interval 0.68 to 0.8. Synonymous variants: 248 observed, 244.48 expected, observed/expected ratio (o/e) 1.01, 90% interval 0.91 to 1.13.
Homologues: Orthologues: chimpanzee LCAT (100% identical), macaque LCAT (99% identical), rabbit LCAT (93% identical), pig LCAT (92% identical), guinea pig LCAT (91% identical), rat Lcat (87% identical), mouse Lcat (86% identical), tropical clawed frog lcat (63% identical), zebrafish lcat (58% identical). Paralogues in human: PLA2G15 (45% identical).
Diseases named in the same sentence as LCAT in open-access papers:
LCAT is named in the same sentence as 197 diseases in open-access papers, as found by Europe PMC text mining. Sharing a sentence is not in itself a finding about the gene and the disease. The quoted sentences say what the papers report.
atherosclerosis (58 papers, 2010 to 2025). A disease characterized by the build-up of fatty material and calcium deposition in the arterial wall resulting in partial or complete occlusion of the arterial lumen. "To date, LCAT plays an important role in atherosclerosis and is associated with abdominal subcutaneous fat and abdominal visceral fat." (PMID 38918701, 2024). "It paves the way for the rational development of new therapies for LCAT deficiency, atherosclerosis, and acute coronary syndrome." (PMID 36903601, 2023). "In individuals with very low high-density lipoprotein (HDL-C) cholesterol, such as Tangier disease, LCAT deficiency, and familial hypoalphalipoproteinemia, there is an increased risk of premature atherosclerosis." (PMID 36651718, 2023). "In previous studies, the reduction of LCAT activity was shown to be associated with atherosclerosis." (PMID 36494696, 2022). "It inhibited atherosclerosis in mice expressing human LCAT, which was associated with enhanced the RCT process." (PMID 35918332, 2022). "Due to the vital role in RCT, variations in LCAT activity seem to be naturally implicated in atherosclerosis prevention or development." (PMID 36588724, 2022). "AIP has been considered a reliable index for atherosclerosis because it is known that the smaller the HDL-c particle, the higher the risk of esterification by lecithin cholesterol acyltransferase and consequently atherosclerosis development." (PMID 27812605, 2016). "LCAT-based therapies, such as small molecule positive allosteric modulators (PAMs), against LCAT deficiencies and atherosclerosis hold promise, although their efficacy against atherosclerosis remains challenging." (PMID 39478139, 2024). "Divergent results between studies remain unclear about whether low LCAT activity, genetically determined, is associated with increased preclinical atherosclerosis." (PMID 36651718, 2023). "It has been demonstrated previously that LACT deficiency, also caused by pathogenic alterations in the LCAT gene, may be associated with increased risk of atherosclerosis and coronary artery disease." (PMID 32118038, 2020). "In golden Syrian hamsters, the loss of LCAT activity led to dyslipidemia and atherosclerosis." (PMID 30845751, 2019). "Data concluded that recombinant LCAT administration may represent a novel approach for the treatment of atherosclerosis and the dyslipidemia associated with low HDL." (PMID 23781332, 2013). "Several investigations suggest that in the presence of abnormal lipid metabolism that can cause ASCVD, RCT may be activated and LCAT may stimulate esterification of free cholesterol, possibly resulting in changes in the direction toward suppressed progression of atherosclerosis." (PMID 30518338, 2018). "However, according to the results of evaluation of the LCAT activity using the currently available assay methods, including both the exogenous and endogenous substrate methods, it appears quite likely that an increased LCAT activity is associated with the progression of atherosclerosis." (PMID 30518338, 2018). "Thus, measurement of the LCAT activity may be useful for predicting ASCVD in patients at a high risk for progression of atherosclerosis." (PMID 30518338, 2018). "Since LCAT activators are useful for treating atherosclerosis, FLD, and FED, the focus of drug development is on the LCAT activators." (PMID 38455763, 2024). "Given the persistent global threat posed by cardiovascular diseases, particularly atherosclerosis, comprehending the mechanisms connecting lecithin, LCAT, and cardiovascular health is crucial." (PMID 39001966, 2024). "A novel LCAT activator (DS-8190a) was shown to prevent the progression of plaque accumulation in atherosclerosis models." (PMID 39154733, 2024). "With this model we discovered that antidiabetic SGLT2 inhibitors canagliflozin and dapagliflozin possess a clinically novel potentially atherosclerosis preventing mechanism of action: the allosteric activation of LCAT." (PMID 39478139, 2024).
atherosclerosis (continued). "Conversely, other research indicates that LCAT deficiency and reduced HDL-C levels reduce the risk of atherosclerosis, coronary artery disease or ischemic heart disease." (PMID 39001966, 2024). "Lower LCAT activity is commonly associated with low HDL cholesterol levels and an increased risk of atherosclerosis and cardiovascular disease development." (PMID 37511116, 2023). "Most data from preclinical studies suggest that increasing the amount of LCAT stimulates reverse cholesterol transport and reduces atherosclerosis." (PMID 36651718, 2023). "ApoA-IV prevents thrombosis by inhibiting platelet aggregation and hyperactivity, enhances cholesterol efflux by ABCA1, activates LCAT, prevents the oxidation of LDL molecules, and attenuates the risk for the development of atherosclerosis." (PMID 36297390, 2022). "Compound A is the first identified small molecular activator of LCAT that can covalently bind to residue C31 of LCAT, and has been shown to increase LCAT activity in vitro with unclear function on atherosclerosis." (PMID 35918332, 2022). "Increased cholesteryl esters by LCAT reduces diet-induced atherosclerosis in scavenger receptor class B member I knockout mice." (PMID 35282441, 2022). "Despite its central function in HDL remodeling and maturation, the role of LCAT in the pathogenesis of atherosclerosis is still debated." (PMID 33807918, 2021). "The activity of an enzyme responsible for clearing cholesterol from peripheral cells, lecithin cholesterol acyltransferase (LCAT), is significantly decreased in atherosclerosis and AD." (PMID 34830148, 2021). "LPC, a major phospholipid of oxLDL that is closely related with the tissue damage caused by atherosclerosis is generally produced under various physiological conditions by endogenous LP-PLA2 and LCAT-mediated hydrolysis of lipoproteins." (PMID 32727012, 2020). "While the role of LCAT in atherosclerosis remains elusive, the consensus is that a continued study of both the enzyme and disease will lead toward better treatments for patients with heart disease and FLD." (PMID 32482717, 2020). "In contrast with ACAT-deficient mice, the animals in which LCAT expression was suppressed showed an increased cholesterol oxidation, reduced HDL and sustained atherosclerosis development." (PMID 31101130, 2019). "Genetic deficiency of LCAT leads to the accumulation of nascent pre-β HDL in the circulation and development of atherosclerosis and acute coronary syndrome." (PMID 30845751, 2019). "In this study, we investigated the factors involved in the progression of atherosclerosis with our attention focused on the serum LCAT activity, TPL-related makers and LDL particle size." (PMID 30518338, 2018). "Lecithin-cholesterol acyltransferase (LCAT) is believed to be involved in reverse cholesterol transport, which is known to play a key role in suppression of atherosclerosis." (PMID 30518338, 2018). "In fact, no unified view has been obtained so far, based on carotid artery ultrasound study reports, as to the relation of the serum LCAT activity with progression/suppression of atherosclerosis." (PMID 30518338, 2018). "We propose that LCAT activation represents a novel therapeutic strategy for the treatment of dyslipidemia and atherosclerosis through the mechanism of favorably modulating HDL metabolism and promoting RCT." (PMID 26644477, 2016). "For instance, rabbits with LCAT overexpression showed strong resistance to developing atherosclerosis when fed a high cholesterol diet." (PMID 26644477, 2016). "Notably, current research on APRT has predominantly focused on the relationship between APRT deficiency and childhood renal dysfunction, while studies on LCAT have primarily centered on its cardioprotective effects in male populations with atherosclerosis." (PMID 40927188, 2025). "Also, the intricate association between increased LCAT activity and a reduction in LDL particle size in the context of atherosclerosis warrants further investigation." (PMID 39001966, 2024).
atherosclerosis (continued). "LCAT has been extensively studied in atherosclerosis over the last few decades." (PMID 38918701, 2024). "Lecithin-cholesterol acyltransferase (LCAT) serves as a pivotal enzyme in preserving cholesterol homeostasis via reverse cholesterol transport, a process closely associated with the onset of atherosclerosis." (PMID 39478139, 2024). "Based on the fact that recombinant human LCAT (rhLCAT) can improve lipid metabolism, rhLCAT has been developed mainly for the treatment of cardiovascular diseases, such as atherosclerosis, and has entered phase II clinical trials with promising results from earlier phase studies." (PMID 36967758, 2023). "LCAT-mediated cholesterol esterification is a rate-limiting step in the reverse transport of cholesterol and is considered a potential target for the prevention of atherosclerosis." (PMID 36967758, 2023). "Gene regulatory network analysis identified specific liver regulators related to lipid metabolism (SC5D, LCAT and HMGCR), inflammation (IL1A) and fibrosis (PDGF, COL3A1), linked to a set of aorta target genes related to vascular inflammation (TNFA) and atherosclerosis signaling (CCL2 and FDFT1)." (PMID 35897797, 2022). "Even though studies in murine models did not lead to conclusive results about the impact of LCAT deficiency and overexpression on atherosclerosis, indications are ascribing a more likely atheroprotective role of LCAT in more humanized animal models." (PMID 36297390, 2022). "Although altered activity of LCAT has been observed in several diseases such as cancer and diabetes, the relationship between variations in plasma LCAT activity and subclinical atherosclerosis is unclear." (PMID 34070169, 2021). "However, despite the fact that LCAT deficiencies are associated with low HDL-C and esterified CHOL levels, the role LCAT deficiency in the development of atherosclerosis is unclear." (PMID 29438987, 2018). "In addition, adenovirus-mediated LCAT overexpression in rabbits was associated with a roughly 2-fold increase in HDL-C, inhibition of atherosclerosis, and increased cholesterol unloading from atherosclerotic lesions." (PMID 26644477, 2016). "A few other studies failed to capture an association between low LCAT levels and increased atherosclerosis or, conversely, an association of increased LCAT activity with lower CVD risk." (PMID 26644477, 2016). "In another study, transgenic rabbits that lacked either one or both copies of a functional LDL receptor revealed that LCAT may have the ability to affect atherosclerosis through the LDL receptor pathway." (PMID 26644477, 2016). "An understanding of the mechanism of the suppression of cholesterol esterification in interstitial fluid may shed light on the regulation of LCAT, and aid the development of new approaches to the prevention of atherosclerosis by modulation of HDL metabolism." (PMID 27471469, 2016). "However, another in vivo study reported that CETP expression reduced atherosclerosis in lecithin cholesterol acyltransferase (LCAT) transgenic mice and a further study revealed that CETP offset the deleterious effect of LCAT." (PMID 25366166, 2014). "Finally, LCAT is the only enzyme that can esterify cholesterol in plasma, which determines maturation of high-density lipoprotein as a key enzyme for reverse cholesterol transport with reports of its role in atherosclerosis, cholesterol deposition, and kidney." (PMID 35872941, 2022). "Thus, LCAT has been shown to be closely related to Atherosclerosis." (PMID 36588724, 2022). "Reduced LCAT activity, together with reduced cholesterol efflux and lipoprotein oxidation, might contribute to the close association between MetS, impaired RCT, and atherosclerosis." (PMID 35743227, 2022). "Absence of LCAT for instance, one of the hepatic key regulators that in our study was found to be down-regulated on high-fat diet and linked to several aortic key regulators, accelerates atherosclerosis in hamsters." (PMID 35897797, 2022).
atherosclerosis (continued). "Using this method, we identified several hepatic regulators related to lipid metabolism (SC5D, LCAT and HMGCR), inflammation (IL1A) and fibrosis (PDGF and COL3A1) that were linked to a set of aorta target genes related to vascular inflammation (TNFA) and atherosclerosis signaling (CCL2 and FDFT1)." (PMID 35897797, 2022). "Most data from preclinical studies suggest that increasing LCAT stimulates RCT and reduces atherosclerosis." (PMID 36967758, 2023). "In mice, the transient overexpression of the LCAT gene can reduce macrophage accumulation, oxidation of LDL, and atherosclerosis." (PMID 36456907, 2022). "On the other hand, too high LCAT overload gives rise to very large HDLs rich in CEs (apoE-rich HDL1), dysfunctional in CE delivery to the liver, which can lead to increased atherosclerosis." (PMID 36297390, 2022). "In future studies, we will need to investigate the molecular mechanisms, whereby APOA4, LCAT, PON1, and PON3 protect against atherosclerosis in CKD and if improving their levels in HDL will reverse CKD atherosclerosis in model systems." (PMID 34634315, 2021). "By contrast, the role of LCAT, which is of major importance in HDL-maturation and plasma HDL levels, is controversial as regards its possible involvement in atherosclerosis." (PMID 34131781, 2021). "Furthermore, LCAT overexpression improved LDL receptor-mediated reverse cholesterol transport, leading to regression of atherosclerosis, suggesting synergistic effects of MEDI6012 with statins." (PMID 36651718, 2023). "Given their protective functions against atherosclerosis and their yet unidentified roles in kidney disease, APOA4, LCAT, PON1, and PON3 may represent therapeutic targets for CVD in CKD patients." (PMID 34634315, 2021). "Because 27C3 and other identified agonistic antibodies do not cross-react with rabbit or rodent LCAT species, we were unable to evaluate the impact of these antibodies on atherosclerosis in these well established preclinical disease models." (PMID 26644477, 2016). "The status of LCAT activity is a controversial issue in atherosclerosis and has not yet been investigated in T2DM with CAD." (PMID 26268997, 2015). "Patients with deficiency of plasma lecithin cholesterol acyltransferase (LCAT) enzyme have HDL-C concentrations lower than 0.40 mmol/L (15 mg/dL), but they do not show signs of an obvious increase in the risk of atherosclerosis." (PMID 24222847, 2013). "Tx patients without statin and with lower TG but higher HDL-C, and disturbed lipoprotein composition of ApoAI and apoAII in HDL particle can decrease LCAT, increase LDL cholesterol, aggravate renal graft, and accelerate atherosclerosis and chronic heart disease." (PMID 23479335, 2013). "Tx patients without statin and with lower triglycerides but higher HDL cholesterol concentration and disturbed lipoprotein composition of ApoAI and apoAII in HDL particle can decrease LCAT, increase LDL cholesterol, aggravate renal graft, and accelerate atherosclerosis and chronic heart diseases." (PMID 23479335, 2013). "However, in support of an important role for PON1, genetic deficiency of neither apoA1 nor LCAT in humans is, unlike PON1 deficiency, conspicuously associated with premature atherosclerosis." (PMID 36873390, 2023). "Moreover, apoE can provide protection from atherosclerosis by promoting the in vivo biogenesis of functional spherical apoE-containing HDL particles (HDL-apoE) with the participation of ABCA1 and LCAT (lecithin-cholesterol acyltransferase) independently of apoA-I." (PMID 30282955, 2018). "Thus, although we did not observe changes in atherogenic lipoproteins, the observed changes in these mediators (LCAT, HDL) of RCT suggest ML may also protect against atherosclerosis." (PMID 28640194, 2017).